ADGB (androglobin)
Description:
Probable chimeric globin with a bis-histidyl six-coordinate heme-iron atom through which it could bind dioxygen, carbon monoxide and nitric oxide. Required for sperm flagellum formation and maturation of elongating spermatids, thus playing an essential role in male fertility.
Synonyms: C6orf103; FLJ23121; dJ408K24.1; CAPN16
Tractability: No criterion of Open Targets' tractability assessment is met for any kind of drug.
Gene: Protein-coding gene on chromosome 6 (146,598,967 to 146,815,462, forward strand). Ensembl gene ENSG00000118492.
Subcellular location: Cell projection, cilium, flagellum
Subcellular location (Human Protein Atlas): Mid piece
Gene Ontology:
Molecular function: calcium-dependent cysteine-type endopeptidase activity; heme binding; oxygen binding
Biological process: spermatid development; proteolysis; spermatogenesis
Cellular component: sperm annulus; sperm midpiece; motile cilium; sperm flagellum
Genetic constraint (gnomAD): Loss-of-function variants: 119 observed, 147.21 expected, observed/expected ratio (o/e) 0.81, 90% interval 0.7 to 0.94. The upper end of that interval is the gene's LOEUF score, 0.94, which puts it in group 3 of 6, group 1 being the genes least tolerant of losing a copy. Missense variants: 1,599 observed, 1,601.5 expected, observed/expected ratio (o/e) 1, 90% interval 0.96 to 1.04. Synonymous variants: 539 observed, 548.79 expected, observed/expected ratio (o/e) 0.98, 90% interval 0.91 to 1.05.
Homologues: Orthologues: chimpanzee ADGB (98% identical), macaque ADGB (96% identical), dog ADGB (81% identical), pig ADGB (77% identical), rabbit ADGB (76% identical), rat Adgb (76% identical), mouse Adgb (75% identical), tropical clawed frog adgb (45% identical), zebrafish adgb (35% identical), Caenorhabditis elegans clp-8 (7% identical), Caenorhabditis elegans clp-1 (6% identical), Caenorhabditis elegans clp-6 (6% identical), and 4 more. Paralogues in human: CAPN15 (9% identical), CAPN1 (9% identical), CAPN3 (9% identical), CAPN2 (9% identical), CAPN11 (8% identical), CAPN8 (8% identical), CAPN9 (8% identical), CAPN14 (8% identical), CAPN5 (8% identical), CAPN12 (7% identical), CAPN13 (7% identical), CAPN10 (7% identical), and 8 more.
Diseases named in the same sentence as ADGB in open-access papers:
ADGB is named in the same sentence as 9 diseases in open-access papers, as found by Europe PMC text mining. Sharing a sentence is not in itself a finding about the gene and the disease. The quoted sentences say what the papers report.
glioma (2 papers, 2020 to 2021). A benign or malignant brain and spinal cord tumor that arises from glial cells (astrocytes, oligodendrocytes, ependymal cells). "An in vitro cell culture study suggested that ADGB could act as an oncogene in glioma formation and an ADGB knockdown could inhibit the growth of glioma cell lines." (PMID 33453283, 2021).
male infertility (2 papers, 2024 to 2025). The inability of the male to effect fertilization of an ovum after a specified period of unprotected intercourse. "Two independent studies with human data of male infertility patients with variants in the ADGB gene further underscore the functional relevance of our data." (PMID 38786048, 2024). "Genetic variants in human ADGB have been linked to male infertility and sperm axonemal disruption." (PMID 41292827, 2025). "Indeed, we showed that androglobin expression is associated with late stages of spermatogenesis, and Adgb-deficient mice display male infertility, as evidenced by a total lack of functional sperm." (PMID 38786048, 2024).
infertile (1 paper, 2021). "An important role of ADGB in spermatogenesis was supported by analysis of published microarray data revealing that endogenous levels of human ADGB mRNA were lower in the testes of infertile men versus their healthy counterparts." (PMID 33453283, 2021).
Obesity (1 paper, 2020). Accumulation of substantial excess body fat. "Obesity group also showed a lower mutation frequency of PLCG2, STK31, ADGB, and so on." (PMID 33197880, 2020).
pancreatic cancer (1 paper, 2022). "In addition, a recent study has reported that STXBP5-AS1 inhibited cancer stem cell phenotypes of pancreatic cancer cells through EZH2/ADGB pathway." (PMID 35802620, 2022).
cancer (2 papers, 2022 to 2025). A tumor composed of atypical neoplastic, often pleomorphic cells that invade other tissues. "These genes were presumably involved in cancer (SMG6, HCK), cellular growth (CPVL), reproduction (ADGB, CRISP1, CTTNBP2NL, WDR78), and nervous system (AUTS2, CNTNAP2, CPVL, SRGAP2)." (PMID 40149444, 2025).
infection (1 paper, 2023). The state of being infected such as from the introduction of a foreign agent such as serum, vaccine, antigenic substance or organism. "However, the effects of ADGB and SULT1A2 in infection and immune responses remain to be clarified." (PMID 38020709, 2023).
tumor (1 paper, 2020). "In summary, we provided experimental data supporting the tumor suppressor function of STXBP5-AS1 in PC via inhibiting chemoresistance and stem cell-like properties, which was greatly mediated by epigenetic silencing of its neighboring ADGB." (PMID 33160411, 2020).
ADGB also shares sentences with these, for which no sentence is quoted: ciliopathy (1 paper).